HIF1A (hypoxia inducible factor 1 subunit alpha)
Diseases named in the same sentence as HIF1A in open-access papers (continued):
Sharing a sentence is not in itself a finding about the gene and the disease.
tumor (continued). "For example, neuroblastoma specimens frequently have strong expression of HIF-2α protein in well-vascularized tumor areas, whereas HIF1α is most restricted to perinecrotic regions." (PMID 26910842, 2016). "Taken together, our studies demonstrate that a methylation/demethylation cycle is involved in the regulation of HIF-1α stability in hypoxia signalling pathways, resulting in enhanced retinal angiogenesis and tumour vascularization in vivo in Hif1aKA/KA mice." (PMID 26757928, 2016). "Animals were sacrificed 30 minutes post-treatment (3 per group) and expression of hypoxia-inducible-factor-1α (HIF1α) protein measured by real time quantitative polymerase chain reaction and Western blot analysis of the excised tumour tissue." (PMID 28036332, 2016). "In both pT1M0 and pT1M1 tumours, a moderate-to-good positive correlation (r=0.4–0.7; Spearman's rank correlation coefficient) for HIF-1α and HIF-2α as well as co-expression of phospho-mTOR S2448 and phospho-S6RP S235/236 was found." (PMID 27291893, 2016). "In conclusion, lncRNA CPS1-IT1 acts as a tumor suppressor in HCC by reducing HIF-1α activation and suppressing EMT." (PMID 27248828, 2016). "HIF-1α is therefore the key player that allows cells to adapt to hypoxic conditions, and in case of tumor cells, to become less likely to respond to cytotoxic therapy." (PMID 27780920, 2016). "For example, it has been demonstrated that lactate promotes HIF-1α accumulation in a hypoxia-independent manner in tumor cells through the inhibition of proline hydroxylation, driving expression of downstream effectors such as VEGF, and, potentially, CAIX." (PMID 27066484, 2016). "Additional studies also highlighted a critical role for reductive carboxylation, mediated by hypoxia or HIF-1α, in promoting the lipogenic phenotype and supporting tumour growth." (PMID 27058900, 2016). "YC-1 is a promising antiangiogenic anticancer agent that functions by targeting HIF-1α and has effectively prevented tumor growth in immunodeficient mice grafted with five types of human tumor cells and in Hep3B cells." (PMID 26767504, 2016). "Together, these results demonstrate a role for HIF-1α methylation in regulating protein stability, thereby modulating biological output including retinal and tumour angiogenesis, with therapeutic implications in human cancer." (PMID 26757928, 2016). "On the other hand, TLR3 was detected at much lower levels in tumor samples displaying a low level of CAIX/HIF-1α." (PMID 27791989, 2016). "A more general finding was first proposed by Semenza and co-workers demonstrating that HIF-1α controls the expression of 100 genes involved in tumor progression and this number increased to more hundred genes during the last years." (PMID 27044404, 2016). "CAFs, the most abundant cell type in the tumor stroma, have been demonstrated to have an important role in cancer initiation and the metastatic step, and also CAFs are induced by HIF-1α and a key source of VEGF, which is essential in tumor angiogenesis." (PMID 27634881, 2016). "Recent researchers have also observed a positive correlation between hypoxic microenvironment and PC and revealed hypoxia-inducible factor-1α (HIF-1α) expression in MS as a predominant factor that controls the tumor stem cell phenotype." (PMID 26831659, 2016). "Other studies found that HIF-2α can combine with enhancers of VEGF gene more easily which is highly relevant to the expression of VEGF mRNA and that HIF-1α regulated tumor growth mainly by energy protection mechanisms under the hypoxia environment." (PMID 27413748, 2016). "In conclusion, this preliminary study confirms that there are 2 main histological types of CRLM, each with a distinct tumor-liver interface, intratumoral glandular and vascular pattern, and significantly different expression of HIF-1α, VEGF, and MVD." (PMID 26937938, 2016).
tumor (continued). "Among the control tumors, the expression of HIF-1α was observed occasionally in three of the 11 tumors (staining: +), and in many tumor cells in the other eight (staining: ++)." (PMID 27244880, 2016). "Collectively, these observations strongly argue for the functional contribution of NQO1 in stabilizing HIF-1α which, in turn, enhances tumour growth in vivo." (PMID 27966538, 2016). "AREG, an epidermal growth factor receptor ligand, is regulated by prolyl-4-hydroxylase domain enzyme 2 (PHD2), a regulator of the stability of HIF-1α that is involved in tumor progression and angiogenesis." (PMID 27435599, 2016). "Knocking down HIF1α expression using shRNA partially inhibited tumor formation in mice and increased the survival of mice bearing tumors." (PMID 27259264, 2016). "One mechanism of tumor resistance to antiangiogenic therapy (e.g. bevacizumab) is upregulation of hypoxia-inducible factor 1α (HIF-1α), which mediates adaptive responses to hypoxic conditions." (PMID 26933802, 2016). "To correlate this finding with tumor malignancy, we haveconfirmed HIF-1α, HIF-2α, and EGFR expression in sections from the samefrozen sample by western blot analysis." (PMID 27303300, 2016). "Intratumoural hypoxia induces HIF-1α and promotes tumour progression, metastasis and treatment resistance." (PMID 27934968, 2016). "Both HIF-1α accumulation and the tumor-promoting metabolic state are required for DKG-promoted tumor repopulation capacity in vivo." (PMID 27058900, 2016). "Knockdown of either Nrf2 or HIF-1α decreased formation of capillary-like structures as well as tumor cell colonies." (PMID 27286880, 2016). "Having documented that hypoxia induced 14-3-3ζ expression regulated HIF-1α expression, we sought to elucidate the role of 14-3-3ζ in tumor cell behavior." (PMID 26910835, 2016). "The expressions of these proteins in 14-3-3ζ down-regulated tumor cells was rescued by ectopic HIF-1α expression under hypoxic conditions." (PMID 26910835, 2016). "A better understanding of septin-mediated stabilization of HIF-1α opens the way to new therapeutic approaches to target “normoxic” tumor cells." (PMID 28066764, 2016). "It is reported that endostatin combined with radiotherapy can significantly inhibit the activity of HIF-1α in tumor cells, thus increasing the activity of antitumor angiogenesis and metastasis." (PMID 26853843, 2016). "Our results revealed that ZnPP possessed higher inhibitory effects than hemin on HIF-1α expression and proliferation of tumor cells, suggesting that ZnPP is a therapeutic candidate for treatment of cancers." (PMID 26822586, 2016). "HIF-1α is the most ubiquitously expressed transcription factor and its increased level of has been positively correlated with tumor progression and poor prognosis in patients with brain cancers." (PMID 26880981, 2016). "The oncogenic potential of the transcription factors c-Myc and HIF1α has great influence on tumor energy metabolism and triggers tumor progression." (PMID 27626684, 2016). "Here we revealed previously unsuspected pro-tumorigenic roles for NQO1 that essentially increase the expression of the HIF-1α protein, a central transcriptional factor of the hypoxic response of cancer cells to the hypoxic tumour microenvironment." (PMID 27966538, 2016). "The HIF1A genotypes were significantly correlated with primary tumor size (T stage) (P=0.002) and lymph node metastasis (P=0.022)." (PMID 26872370, 2016). "Hypoxia, an important feature of the tumour microenvironment, is known to mediate tumour VM through HIF-1α." (PMID 27346985, 2016). "After validation of the WNT11 antibody, we observed that WNT11 is elevated in the area of tumor hypoxia where HIF-1α and pimonidazole staining are colocalized." (PMID 26861754, 2016). "We also observed that the cancer tissues expressing high NQO1 level also express higher-level of HIF-1α protein than tumours expressing relatively low NQO1." (PMID 27966538, 2016).
tumor (continued). "Among the many regulatory factors in tumor angiogenesis, hypoxia-inducible factor-1α (HIF-1α) and vascular endothelial growth factor (VEGF) play vital roles in this process." (PMID 26985249, 2016). "Oncogenes and tumour suppressors are also critical activators of HIF-1α, leading to increased translation (PI3K, PTEN) and stabilisation (VHL) of HIFs in an O2-independent manner." (PMID 26099350, 2016). "This immune adaption is dependent on the HIF-1α-mediated induction of metalloproteinase ADAM-10 in tumor cells." (PMID 27044404, 2016). "The fact that secreted Hsp90α protects tumour cells from apoptosis supports the notion that HIF-1α antagonizes the apoptotic signals from hypoxia." (PMID 26846992, 2016). "A recent study showed that PKM2 expression is induced by an mTOR/HIF-1α/c-Myc glycolysis signaling network, promoting aerobic glycolysis in tumor cells." (PMID 27492148, 2016). "Although HIF-1α and corresponding inducible targets are lower in BCSCs relative to tumor at baseline, CD49fhiCD24hi and CD49flowCD24hi cell types expressed higher levels of these transcripts following exposure to hypoxia, as expected." (PMID 26316122, 2015). "In CK-160 tumors, pimonidazole-positive cells and CAIX-positive cells were observed both adjacent to necroses and in some regions consisting predominantly of viable tissue, while strong staining for HIF-1α was seen throughout the tumor tissue." (PMID 26502718, 2015). "The results showed that MCF-7/HIF-1α cells exhibited larger xenograft tumor formation compared with those formed by MCF-7/vector cells." (PMID 25929338, 2015). "HIF1α is largely responsible for activating the transcription of target genes that drive various features of aberrant tumor metabolism, such as increased glucose uptake, increased glycolysis and lactate production, and decreased mitochondrial respiration." (PMID 25830305, 2015). "Loss of VHL function upregulates HIF-1α, a transcription factor that leads to an overexpression of VEGF and drives tumor angiogenesis." (PMID 26021863, 2015). "Compared with the control cell line, MCF-7/hyp cells display an increased HIF-1α expression, a higher potential for tumor formation and less sensitivity to the anti-estrogen agent, fulvestrant." (PMID 25929338, 2015). "Protein levels of hypoxia inducible factor 1α (HIF-1α), a key regulator of glycolysis in tumor cells, were also measured and showed to be decreased by 40% in siRNA-SLC cells." (PMID 25797253, 2015). "When tumor cells are exposed to hypoxia, a new equilibrium is sought between HIF1α and c-MYC for control over translation." (PMID 26501324, 2015). "Pimonidazole was used as a hypoxia marker, and tumor hypoxia, HIF-1α expression, and CAIX expression were detected by immunohistochemistry." (PMID 26502718, 2015). "Relatively higher expression of DNA methyl-transferases (DNMT1 and DNMT3b) and HIF-1α genes (34-50%, P<0.05) were also detected in tumor tissues." (PMID 25938433, 2015). "HIF-1α is regulated during several cellular biological responses and plays a pivotal role in angiogenesis and tumor progression." (PMID 26378810, 2015). "As expected, immunohistochemical staining showed that HIF-lα was overexpressed in tumor tissue derived from mice in the Lenti-HIF1α group (P = 0.001) and downregulated in the Lenti-HIF1α-siRNA group (P = 0.016)." (PMID 25811359, 2015). "In mice injected with HIF-1α-overexpressing cells, but given GANT61, the tumor volume was remarkably smaller (P < 0.0001), suggesting that the positive effect of HIF-1α on tumor growth was antagonized via inhibiting the SHH pathway." (PMID 25811359, 2015). "HIF-1α increases migration of tumor cells promoting epithelial- to-mesenchymal transition (EMT), a mesenchymal phenotype expressing invasive and motogenic properties, crucial in local invasiveness and secondary organ colonization." (PMID 25897425, 2015). "Levels of OPN protein expression were significantly correlated with HIF-1α protein levels in HCC tumor tissue samples." (PMID 25749383, 2015).
tumor (continued). "The tumor-specific conditions include genetic changes leading to stabilization of HIF-1α under normoxic conditions, alterations of the HIF-1α degradation pathway, and activation of HIF-1 target genes by hypoxia-independent mechanisms." (PMID 26502718, 2015). "HIF1α plays a critical role in hypoxia to improve glycolysis, oxygen delivery, and angiogenesis for tumor cells." (PMID 25622105, 2015). "The HIF-1α downstream target VEGF also plays an important role in tumor angiogenesis and is an attractive chemotherapeutic target." (PMID 26378810, 2015). "In fact, HIF-1α and HIF-2α were first considered as essential for ccRCC progression but several studies tend toward an oncogenic role for HIF-2α in ccRCC and a tumor suppressor function for HIF-1α." (PMID 26579493, 2015). "Hypoxia-inducible factor-1α (HIF-1α) enhances tumor cell motility by activating the epithelial-to-mesenchymal transition (EMT), which is considered a prerequisite for metastasis." (PMID 26528854, 2015). "Alternatively, TAp73 activation in tumor-suppressive contexts or genotoxic-stress contexts, such as upon exposure to DNA-damaging agents, would be able to suppress HIF1-α expression through MDM2-mediated degradation (top right)." (PMID 26711266, 2015). "HIF-1α is broadly expressed in many human cancers and frequently correlates with poor prognosis; it affects many key aspects of tumor aggressiveness and represents an attractive target for anti-cancer therapies." (PMID 26512778, 2015). "There is clinical evidence of an effect of NTG on expression of HIF-1α, with immunostaining of tumour samples showing decreased levels of expression of HIF-1α and VEGF in NSCLC patients treated with NTG patches compared to non-treated controls." (PMID 26435741, 2015). "Tumor hypoxia is significant in promoting tumor progression and resistance to therapy, and hypoxia-inducible factor 1α (HIF-1α) is essential in the adaptive response of cells to hypoxia." (PMID 25789026, 2015). "Although the stabilization of Hif1α during hypoxia is generally pro-proliferative as stabilization of Hif1α influences the survival of tumor cells, Hif1α has also tumor-inhibiting properties." (PMID 26496038, 2015). "HIF1α is one of the central regulators of transcriptional control in tumor cells’ response to hypoxic conditions." (PMID 26292663, 2015). "Positive expression of HIF-1α was found in 57.7% of all the tumor samples from all clinical stages, and the degree of positive staining for SHH, PTCH1 and GLI1 was 64.8%, 46.5%, and 54.9%, respectively." (PMID 25811359, 2015). "Previous studies have suggested that microRNA-107 (miR-107) regulates cell migration in tumor and promotes Hypoxia Inducible Factor 1α (HIF1α) regulated angiogenesis under hypoxia." (PMID 26294080, 2015). "Hypoxia-inducible factor α (HIF1α) is one of the transcriptional factors frequently activated in the tumors and widely involved in the tumor growth, progression, and resistance to chemotherapy." (PMID 26309161, 2015). "The combination of cisplatin with YC-1, which promotes STAT3 degradation and reduces HIF-1α protein levels, results in enhanced sensitivity of hepatocellular carcinoma cells to cisplatin and suppression of tumor growth." (PMID 26106584, 2015). "HIF-1α is an important transcription factor for tumor growth, invasion, angiogenesis, metabolism and drug resistance." (PMID 25544770, 2015). "HIF-1α also increases expression of genes involved in glycolysis, to adapt the tumor to survive under conditions of low oxygen, and genes involved in invasion and metastasis such as Twist1." (PMID 26010887, 2015). "HIF-1α overexpression is frequently observed in tumors and is considered to contribute to tumor cell growth and survival by controlling both glycolysis and angiogenesis." (PMID 26553068, 2015). "When administered in a low-dose, continuous schedule it blocks the expression of tumor cell HIF1α, as first described by Melillo's group." (PMID 26623560, 2015).
tumor (continued). "Hypoxic conditions in the tumor increase the expression of HIF1α, which directly promotes transcription of AXL." (PMID 26328272, 2015). "Expression of HIF-1α was significantly higher in HCC samples with increased tumor size (p < 0.001), vascular invasion (p = 0.025), intrahepatic (p = 0.002) and distant metastasis (p < 0.001)." (PMID 26078356, 2015). "An additional study targeted HIF1α directly with EZN-2968 identifying a variety of patient tumour responses from 94% reduction in HIF1α expression to increased expression." (PMID 25700172, 2015). "A number of reports have established that IL-1β induces the expression of either HIF-1α or NFκB, two of the main hypoxia sensitive pathways, which are involved in tumor progression by promoting angiogenesis, cell migration, and invasiveness." (PMID 26696754, 2015). "HIF-1α is strongly expressed in a variety of malignant tumors and acts as an essential factor to regulate the adaption of tumor cells to hypoxia." (PMID 26292288, 2015). "AT-101 treatment caused intracellular iron chelation and resulted in accumulation of Hif-1α in nerve sheath tumor cells." (PMID 26009874, 2015). "Using ER-negative cells derived from late stage tumors spontaneously formed in MMTV-PyMT mice, deletion of HIF1α has been shown to reduce tumor growth in allotransplantation experiments, while decreasing mammosphere formation in vitro." (PMID 26372732, 2015). "Hypoxia-inducible factor-1α (HIF-1α), a direct mediator of tumor hypoxia, has been shown to mobilize and lead to tumor incorporation of bone marrow-derived vascular modulatory cells, including a small portion of pericyte progenitor cells." (PMID 25875288, 2015). "The tumor-independent mechanisms include differences in the duration and level of hypoxia required for formation of pimonidazole adducts and expression of HIF-1α and CAIX proteins as well as differences in the half-lives of the adducts and the proteins." (PMID 26502718, 2015). "While VEGF expression is an important factor in tumor growth and metastasis, HIF-1α is one of the key factors for VEGF expression." (PMID 25845666, 2015). "In tumor microenvironments, the HIF-1α oxygen-dependent degradation pathway is halted, resulting in elevated levels of HIF-1α." (PMID 25809609, 2015). "Tumor tissues revealed markedly elevated expression of HIF1α and EMT markers Slug and Snail (diffuse pattern), suggesting that the hypoxic microenvironment activated an EMT-like process post-bevacizumab therapy." (PMID 25957416, 2015). "Cetuximab inhibited tumor-induced angiogenesis in vitro and in vivo by significantly downregulating HIF-1α and Notch1." (PMID 25723392, 2015). "Activation of the VEGF gene can also be modulated by the total and nuclear levels of HIF-1α, a transcription factor that plays a central role in tumor progression and angiogenesis." (PMID 25381014, 2015). "HIF-1α is a key regulator of tumor microenvironment, which regulates the transcription of many factors involving with metabolism, inflammatory response, and so on." (PMID 25938544, 2015). "The relative mRNA expression levels of Bax, Bcl-2, VEGF, HIF-1α, and survivin in the tumor tissues were determined by real-time PCR." (PMID 25629230, 2015). "Additional investigation of hypoxic markers, including HIF-1α, as biomarkers of aggressive tumor behavior and as novel therapeutic targets, is warranted." (PMID 25789026, 2015). "Intense HIF-1α nuclear staining was observed in a large proportion of tumor cells, suggesting hypoxia is a common phenomenon in HNSCC." (PMID 25723392, 2015). "The HIF-1α expression sites in the immune cells and tumor cells were significantly more numerous in the HeLaX-E9s than in each control (P<0.05, P<0.01, P<0.001)." (PMID 25874769, 2015). "In conclusion, the present study verified that the expression of EGFR was highly correlated with CD31, CD146 and HIF-1α in human AdCC and also suggested a possible association between EGFR and tumor-derived angiogenesis in this tumor." (PMID 25997612, 2015).